IL2 (interleukin 2)
Diseases named in the same sentence as IL2 in open-access papers (continued):
Sharing a sentence is not in itself a finding about the gene and the disease.
prostate carcinoma (continued). "The recombinant mva called TG4010 expresses both Muc1 (a higher-molecular-weight mucin that is overexpressed in most carcinomas, including prostate carcinoma) and il-2." (PMID 18080016, 2007). "We demonstrate that DNA vaccination with a PSA-coding plasmid vector, given with GM-CSF and IL-2 to patients with prostate cancer, is safe and in doses of 900 μg the vaccine can induce cellular and humoral immune responses against PSA protein." (PMID 15280930, 2004). "The novel finding of this trial is that this DNA/PSA vaccine, given together with GM-CSF and IL-2 to patients with prostate cancer, is safe and in doses of 900 μg can induce PSA-specific immunity." (PMID 15280930, 2004). "In summary, our findings indicate that macrophages mediate CXCL12-CXCR4 ligand-receptor interactions to recruit Tregs and CD8+ effector T cells, leading to functional exhaustion of CD8+ effector T cells through competition for intratumoral IL-2 by Tregs in prostate cancer." (PMID 40698080, 2025). "Synergic effects of interleukin-2 (IL-2) on TCS were also studied in PC3 (prostate cancer) cells." (PMID 35744957, 2022). "Notably, our results further uncovered the oncogenic activities of IL‐2 in prostate cancer cells, wherein IL‐2 was subjected to TRIM66‐positive regulation, and IL‐2 silencing greatly compromised cell proliferation, invasion and migration." (PMID 31981447, 2020). "Overall, these findings demonstrate that CTV-1 priming can enhance cytotoxic responses of patient NK cells toward a metastatic prostate cancer cell line, that is comparable to that of IL-2 stimulation, and that this enhancement appears to be irrespective of disease severity." (PMID 30761160, 2018). "Herein, we explore the phenotype of peripheral blood NK cells in patients with prostate cancer and compare the capacity of CTV-1 cell-mediated priming and IL-2 stimulation to trigger NK cell-mediated killing of the human PC3 (metastatic) prostate cancer cell line." (PMID 30761160, 2018). "The combination therapy strategy between IL-2 and rTCS may bring new hope for patients with prostate cancer." (PMID 27015938, 2016). "Based on the hypothesis that J591 plus IL-2 would work together to effect a positive immune response against prostate cancer, a combination study was initiated." (PMID 21811498, 2012). "In this paper the influence of nanocomposition based on IL-2 in suboptimal concentration and β-cyclodextrin (β-CD) on immunophenotype and cytotoxic activity of ML towards prostate cancer cells of DU 145 and PC-3 types, as well as towards NK-sensitive K-562 cell, was studied." (PMID 22084730, 2011). "Both IL-2 and IFN-α have strong antitumorigenic direct effects against cancer cells, and in vitro cytokine treatment of prostate tumor cell lines can effectively alter a number of prostate carcinoma properties closely associated with tumor invasion and the metastatic phenotype." (PMID 35874516, 2022). "IL-2 may be developed for treating prostate cancer in the future." (PMID 34563040, 2021). "Application of low concentration of interleukin-2 allowing for good clinical efficiency may significantly mitigate the side effects of the drug and enable to develop adoption of immunotherapy for patients with androgen-resistant prostate cancer." (PMID 22084730, 2011). "Recently, our group developed an HLA class I-positive NK feeder cell line originating from the adherent prostate carcinoma cell line PC3 and genetically engineered to express IL-2, 4-1BBL and a membrane-bound form of IL-15 (PC3PSCA-IL-2-4-1BBL-mIL-15d)." (PMID 35628668, 2022). "Our data suggested that IL‐2 was subjected to TRIM66/JAK/STAT regulation, which eventually contributed to the malignant growth and metastasis of prostate cancer cells." (PMID 31981447, 2020).
prostate carcinoma (continued). "Both Treg depletion and IL-2 neutralization have an inhibitory role of CTL, thereby to benefit therapeutic outcomes of prostate cancer treatment." (PMID 26868634, 2016). "To explore the activity of IO in preterminally ill cancer patients, in 2016, we designed a translational exploratory study in end-stage patients suffering from colon, breast, renal and prostate cancers treated with metronomic cyclophosphamide (CTX), low dose interleukin-2 (IL-2) and radiation (RT)." (PMID 33800511, 2021). "To investigate the impact of the inflammatory cytokine IL-2 on antigen-expanded CD8+ T cells, we developed a novel study model, based on the combined use of mature allogeneic monocyte-derived DCs and a PC-3 prostate cancer cell line." (PMID 33327544, 2020). "Therefore, our prediction suggests that Treg depletion is more beneficial than IL-2 neutralization does as an adjuvant or complementary to the combined immunotherapy and ADT for prostate cancer." (PMID 26868634, 2016). "The results from a similar longitudinal study of cytokine expression patterns suggested that serum levels of IL-1, IL-2, IL-6 and IFN-γ in patients with prostate cancer during intensity-modulated radiotherapy may be predictive for acute radiation-induced normal tissue toxicity." (PMID 33149212, 2020). "Similarly to IL-2, IL-21 is expressed by activated CD4+ T-cells and has been described as having anti-tumor effects in mouse models for several different malignancies, including prostate cancer." (PMID 20184734, 2010). "It has been previously shown by our group that IL-15, unlike other therapeutic cytokines such as IL-2 and IL-12, can stimulate expansion and activity of CD8 T cells and NK cells in vitro when they are exposed to prostate cancer cells." (PMID 33777767, 2021). "The univariate analysis of circulating cytokine levels showed that the concentrations of IL-2, IFN-γ, and TGF-β1 in sera of patients with prostate cancer tended to increase, but not statistically significant during course of radiotherapy." (PMID 33149212, 2020). "In vivo anti-tumor activity of armed ATC when co-injected with tumor cells to prevent the tumor development or when injected intratumorally into xenograft model of prostate cancer, armed ATC persist in Beige/SCID mice for 91 days in the spleen and bone marrow without interleukin-2 (IL-2) support." (PMID 23433400, 2013).
renal carcinoma (55 papers, 1991 to 2026). A carcinoma arising from the epithelium of the renal parenchyma or the renal pelvis. "Once such information is available, IL-2 would be a reasonable therapeutic option to directly kill the susceptible renal cancer cells." (PMID 41150778, 2025). "In 1992, the U.S. Food and Drug Administration approved high-dose IL-2 (HD IL-2) as the first immunotherapy for treating various cancers, including renal cancer." (PMID 41150778, 2025). "A clinical trial of DNMT inhibitors in combination with other anticancer drugs, such as IL‐2, interferon‐α and bevacizumab, for renal cancer treatment has been conducted." (PMID 34133843, 2022). "Immunotherapy, such as IFN-α and IL-2, had been the mainstream renal cancer therapy until the 1990s given the immunogenic property of renal cancer." (PMID 33436830, 2021). "In renal cancer, treatment after IL-2 was most commonly a VEGF-TKI agent via clinical trial or standard of care." (PMID 24855563, 2014). "IL-2-induced TATE (corollary to treatment of renal cancer), close proximity of activated eosinophils with bladder tumor cells and the subsequent deposition of eosinophil cationic granules were shown to be associated with a favourable outcome." (PMID 23369060, 2013). "In contrast, the presence of IL-2-induced eosinophilia was considered predictive of the failure of therapy in renal cancer." (PMID 23369060, 2013). "Cryopreserved PBMC from renal carcinoma patients have been shown to retain proliferative capacity to IL-2, capacity to generate cytolytic activity, and secretion of PHA-induced IFN-γ5." (PMID 17156490, 2006). "The only drugs proven to induce regression of the disease are the immunomodulatory agents interferon-α and interleukin-2 (IL-2)." (PMID 16222313, 2005). "The circulating cytokine concentrations following administration of subcutaneous recombinant interleukin 2 (IL-2) in combination with interferon alpha and 5-fluorouracil used to treat advanced renal cancer were studied." (PMID 9192992, 1997). "Moreover, SGK1 activation is deciphered to have a pivotal role in controlling the growth of renal cancer cells via IL-2 mediation." (PMID 36266728, 2022). "IL-2 is another promising target in the horizon of renal cancer treatment." (PMID 34885091, 2021). "Clinical application of IL-2 to exert anti-tumor effects while inhibiting the STAT5 signaling pathway may be an effective treatment strategy for renal cancer." (PMID 31703694, 2019). "Interleukin-2 (used to treat pruritus) can be used as a new therapy to cure renal carcinoma." (PMID 28869563, 2017). "Interactions and optimal sequencing of IL-2 with tyrosine kinase inhibitors, now widely used for the frontline and subsequent treatment of advanced renal cancer, need to be better understood in order to provide the optimal therapy for all patients with this disease." (PMID 24213115, 2011). "Therefore, this project’s main goal involved investigating the potential interaction of IL-2 on renal cancer cells; specifically, we aimed to determine the role of IL-2 in cell death, proliferation and survival of four human RCC cell lines: A-498, ACHN, Caki-1, and Caki-2." (PMID 41150778, 2025). "Similar effects could also be shown in renal cancer in response to preoperative IL-2 application." (PMID 37568571, 2023). "IL-2 activated whole-blood samples (28 VHL-WT-RCC and 23 VHL-MUT-RCC) were evaluated for NK cytotoxicity toward human renal cancer cells A498, VHL-MUT and CAKI-1, VHL-WT." (PMID 30514329, 2018). "Metastatic renal cancer is not sensitive to radiotherapy and chemotherapy, and the effective rate of immunotherapy with interferon and interleukin-2 (IL-2) as first-time clinical treatment is only 15%." (PMID 35846133, 2022). "In addition to the systemic inflammatory response, CRP is a biomarker that predicts the outcome of IL-2 or IFN-α immunotherapy and has been considered in the evaluation of patients with renal cancer." (PMID 32974174, 2020).
renal carcinoma (continued). "Metastatic renal cancer, particularly the clear-cell histology that comprises the majority of cases, is another tumor that is inherently resistant to cytotoxic agents and has shown responsiveness to immune modulators such as IFN-α and IL-2." (PMID 24213115, 2011). "Some renal cancer recurred or metastasized after operation due to the incomplete resection, as a result neither radiotherapy and chemotherapy, nor a interferon (INF-α) and interleukin-2 (IL-2) and other cytokines might be practical for the treatment." (PMID 35368892, 2022). "We believe this approach is not optimal especially in patients with renal cancer as durable remissions are rarely achieved with TKI therapy, and the patient’s performance status is more likely to decline with each successive systemic treatment, thus the opportunity to use IL-2 can be lost." (PMID 24855563, 2014).
schizophrenia (55 papers, 2007 to 2025). A major psychotic disorder characterized by abnormalities in the perception or expression of reality. "Chronically activated macrophages and T lymphocytes with excessive IL-2 and other cytokines have been found as a cause of schizophrenia." (PMID 40833536, 2025). "On the other hand, schizophrenia has been associated with increased serum levels of cytokines such as IL-1R antagonists, IL-2, IL-6, and acute-phase proteins." (PMID 37875841, 2023). "Here, we reviewed a series of studies published from the 1990s and found that IL-2 was closely associated with schizophrenia." (PMID 36138890, 2022). "For example, IL-2 is responsible for mediating toxic reactions, which are the causes of schizophrenia symptoms in patients, and such symptoms resolve after discontinuation of the drug." (PMID 36138890, 2022). "Changes in cytokine levels were also associated with antipsychotic medication, such that higher IL-2 and IL-10 levels were related to higher antipsychotic doses at the time of the scan in the schizophrenia sample." (PMID 29803226, 2018). "In patients with schizophrenia, a significant positive association was identified between antipsychotic dose and both IL-2 (rs = .307, p = 0.040) and IL-10 (rs = .273, p = 0.036)." (PMID 29803226, 2018). "Dysregulation of interleukin-2 (IL-2) has been implicated in the pathogenesis of neurological and neuropsychiatric disorders including multiple sclerosis, Alzheimer’s disease and schizophrenia." (PMID 25961067, 2015). "Schizophrenia is associated with a pro-inflammatory state, with altered blood/cerebrospinal fluid levels of interleukin-2 (IL-2), IL-6, IL-1, IL-10 and tumour necrosis factor (TNF)-α." (PMID 23394123, 2013). "Our review suggests that IL-2 is associated with schizophrenia and plays a role in its pathogenesis, and progression IL-2 and sIL-2R could serve as potential biomarkers of schizophrenia." (PMID 36138890, 2022). "It is appealing that another group of significant pathways including the Fc-epsilon receptor I signaling in mast cells, the TCR signaling in CD4+ T cells and IL2-mediated signaling events highlight the importance of immune system mediated pathways in the key role of schizophrenia susceptibility." (PMID 24564241, 2013). "Activation of STAT1 is downstream of cytokine receptors that signal from specific pro-inflammatory cytokines known to be dysregulated in schizophrenia, such as IFNγ, IL-6, IL-2, and IL-10." (PMID 40259965, 2025). "This study findings indicate that serum IL-8 levels are elevated in individuals with schizophrenia and correlations with baseline serum IL-2 or IL-8 concentrations and therapeutic effectiveness have been identified." (PMID 41200225, 2025). "Our findings support further research with respect to a potential therapeutic role of treatment with IL-2 in patients with schizophrenia who suffer from acute and severe suicidality." (PMID 38549611, 2024). "The change of IL-2 levels in patients with schizophrenia was found to be an increase in patients with schizophrenia in some research, while others found a decrease." (PMID 37189796, 2023). "Compared with healthy people, IL-6 and TNF-α levels were significantly increased in schizophrenia patients, while IL-2, IL-4 and IFN-γ levels were significantly decreased." (PMID 37582716, 2023). "IL-2 can affect many pathological processes which are related to the pathogenesis of schizophrenia, such as the Glu neurotransmitter system." (PMID 36138890, 2022). "A large number of studies have shown that IL-2 levels are different in patients with schizophrenia when compared with the healthy control group." (PMID 36138890, 2022). "IL-2 level is correlated with the pathogenesis and treatment response of schizophrenia, with ample evidence from both vitro and in vivo studies." (PMID 36138890, 2022). "A meta-analysis has shown that IL-2 levels decreased in patients with schizophrenia who were treated with antipsychotics." (PMID 36138890, 2022).
schizophrenia (continued). "Asevedo compared possible correlations between peripheral IL-2 level and symptoms and cognitive function in patients with schizophrenia." (PMID 36138890, 2022). "With the advance in neuroinflammation theory and immunology research on schizophrenia, it is interesting and meaningful to discuss the possible role of IL-2 in schizophrenia." (PMID 36138890, 2022). "Extensive studies have been carried out on the change of the IL-2 level in patients with schizophrenia." (PMID 36138890, 2022). "Among these reasons is the fact that the disease process affects the stability of IL-2 in patients with schizophrenia." (PMID 36138890, 2022). "The significant results included a higher level of IL-2 in patients with OCD compared to controls with ADHD or schizophrenia." (PMID 36061386, 2022). "IL-2, IL-6, IL-10 are known markers of immune status in schizophrenia; and the alterations of their levels are connected with the severity of clinical symptoms and potential clinical implications." (PMID 34025476, 2021). "Other than IL-2 and IL-6, serum levels of IL-8 have also been described as increased in patients with schizophrenia, and correlations between serum IL-2 or IL-8 concentrations at baseline and the therapeutic outcome have been reported." (PMID 33746786, 2021). "It is also worth noting that many of the cytokines altered in the maternal serum are also elevated in the blood of patients with schizophrenia, including IL-1β, IL-2, IL-6, IL-12 and TNF-α." (PMID 30691477, 2019). "In comparison to controls, schizophrenia patients had higher levels of IL-2 (U = 1573.5, p < 0.001) and also the inflammatory cytokines IL-1β (U = 1565.5, p = 0.011), IL-6 (U = 1975.5, p = 0.018), and IFN-γ (U = 2076.0, p = 0.018)." (PMID 29803226, 2018). "Using quantitative RT-PCR, we measured five cytokine mRNAs (IL-1β, IL-2 IL-6, IL-8 and IL-18) from peripheral blood of healthy controls and of people with schizophrenia or schizoaffective disorder (n = 165)." (PMID 28923068, 2017). "A trend towards a significant difference was found between low cytokine controls and low cytokine schizophrenia in IL-2 mRNA expression (p = 0.072)." (PMID 28923068, 2017). "We found an overall decrease in the anti-inflammatory IL-2 mRNA (p = 0.006) and an increase in three serum cytokines, IL-6 (p = 0.010), IL-8 (p = 0.024) and TNFα (p < 0.001) in people with schizophrenia compared to healthy controls." (PMID 28923068, 2017). "In this study, we found a lower level of mRNA for the anti-inflammatory cytokine IL-2 in the blood of people with schizophrenia." (PMID 28923068, 2017). "We found that IL-2 mRNA (ΔΔCt) was significantly decreased in people with schizophrenia (median = 0.64) as compared to healthy controls (median = 1.00), U = 1898, p = 0.006." (PMID 28923068, 2017). "Overall, in people with schizophrenia, we found a lower mRNA expression level of IL-2, believed to be primarily an anti-inflammatory cytokine, supporting earlier findings of decreased IL-2 protein in serum/plasma of people with schizophrenia." (PMID 28923068, 2017). "IL-2 also showed a difference between elevated cytokine controls and elevated cytokine schizophrenia subgroups, with schizophrenia patients being significantly (p = 0.007) lower than controls by 49%." (PMID 28923068, 2017). "Increased serum concentrations of IL-2, IL-6, and IL-8 have been observed in patients with schizophrenia." (PMID 27047333, 2016). "An immune response shifting from Type 1 (including one cytokine interleukin-2(IL2)) to Type 2 (including one cytokine interleukin-10(IL10)) happens in schizophrenia." (PMID 23951054, 2013). "The cellular and molecular module for immune system involving IL-2 pathway and TREM-1/DAP12 pathway were proposed for potential susceptibility for schizophrenia." (PMID 24564241, 2013).